KNCN (kinocilin)
Description:
May play a role in stabilizing dense microtubular networks or in vesicular trafficking.
Synonyms: FLJ32011; KINO; L5
Tractability: Antibody: UniProt predicts a signal peptide or a membrane-spanning region.
Gene: Protein-coding gene on chromosome 1 (46,545,641 to 46,551,647, reverse strand). Ensembl gene ENSG00000162456.
Subcellular location: Membrane
Gene Ontology:
Cellular component: apical plasma membrane; ciliary basal body; cuticular plate; kinocilium; neuronal cell body; apical part of cell; cytoplasm; membrane; microtubule cytoskeleton
Genetic constraint (gnomAD): Loss-of-function variants: 11 observed, 10.24 expected, observed/expected ratio (o/e) 1.07, 90% interval 0.67 to 1.72. The upper end of that interval is the gene's LOEUF score, 1.72, which puts it in group 6 of 6, group 1 being the genes least tolerant of losing a copy. Missense variants: 172 observed, 158.33 expected, observed/expected ratio (o/e) 1.09, 90% interval 0.96 to 1.23. Synonymous variants: 67 observed, 65 expected, observed/expected ratio (o/e) 1.03, 90% interval 0.85 to 1.26.
Homologues: Orthologues: chimpanzee KNCN (98% identical), dog KNCN (91% identical), pig KNCN (84% identical), mouse Kncn (83% identical), rat Kncn (83% identical), guinea pig KNCN (80% identical), rabbit KNCN (79% identical), macaque KNCN (60% identical).
Diseases named in the same sentence as KNCN in open-access papers:
KNCN is named in the same sentence as 1 disease in open-access papers, as found by Europe PMC text mining. Sharing a sentence is not in itself a finding about the gene and the disease. The quoted sentences say what the papers report.
Hydrocephalus (1 paper, 2012). Hydrocephalus is an active distension of the ventricular system of the brain resulting from inadequate passage of CSF from its point of production within the cerebral ventricles to its point of absorption into the systemic circulation. "An additional sample with two events was a fetus with hydrocephalus found to have two duplication CNVs, on chromosome bands 1p33 (including the genes FAAH, DMBX1 and KNCN) and 10q11.22 (containing the genes SYT15, GPRIN2 and PPYR1), but parental samples were not available in this case." (PMID 23056206, 2012).